MDM2 (MDM2 proto-oncogene)
Diseases named in the same sentence as MDM2 in open-access papers (continued):
Sharing a sentence is not in itself a finding about the gene and the disease.
infection (45 papers, 2009 to 2025). The state of being infected such as from the introduction of a foreign agent such as serum, vaccine, antigenic substance or organism. "Concurrently, compared with the control group, the expression levels of circRNA-0172 and MDM2 were downregulated over the course of infection, indicating a time-dependent association between ALV-J infection and the suppression of these host genes." (PMID 41300734, 2025). "To further confirm these findings, we isolated primary hepatocytes from HFHC diet‐fed H‐MDM2‐KO mice and their WT controls, followed by an infection of adenovirus encoding wild‐type MDM2, MDM2‐C642A mutant, or empty control." (PMID 35524581, 2022). "This phenotype was very reminiscent of LY6E knockout, which resulted in an infection kinetic of SARS-CoV-2 that was comparable to MDM2 deletion, i.e., an early onset of the infection signal and a rapid increase of the fluorescent signal." (PMID 37632105, 2023). "Our study illustrates that cellular regulators of ACE2 stability, such as MDM2, play an important role in defining the infection capabilities of SARS-CoV-2." (PMID 37632105, 2023). "In a CRISPR/Cas9-mediated screening approach to identify pro-/antiviral host factors, we found that the depletion of MDM2 substantially increased infection with SARS-CoV-2." (PMID 37632105, 2023). "Here we identify that ACE2 expression levels are regulated by the E3 ligase MDM2 and that MDM2 levels indirectly influence infection with SARS-CoV-2." (PMID 37632105, 2023). "We envisage the early phase of the infection cycle as the optimal time window for MDM2 inhibitors administration." (PMID 35668941, 2022). "In conclusion, our results highlight NS1 as a key determinant in the IAV-induced destabilization of endogenous Mdm2, at early stage of infection." (PMID 29487367, 2018). "We then further investigated the decrease of Mdm2 at early stages of infection (4 hpi), and observed less pronounced IAV-induced destabilization of Mdm2 in the presence of proteasome inhibitor MG132." (PMID 29487367, 2018). "The four recombinant IAV induced significant yet differential decrease on Mdm2 RPL (P < 0.0001) at similar stages of infection, as confirmed by NS1 protein levels." (PMID 29487367, 2018).
infection (continued). "The rapid and global decrease of Mdm2 protein levels at early stages, in the context of a limited infection suggests a possible involvement of cellular paracrine mechanisms that need to be further investigated." (PMID 29487367, 2018). "Conversely, at late stages of infection (24 hpi), Mdm2 estimated half-life was almost 3 times higher in IAV-infected cells compared to mock (60 versus 20 minutes, P < 0.001)." (PMID 29487367, 2018). "As Mdm2 has been initially identified as a required host factor for viral replication, we cannot exclude an ambivalent role of Mdm2 during infection, as a result of its multiple functions and interactions with other host factors." (PMID 29487367, 2018). "Altogether, these results indicate that IAV infection modulates Mdm2 stability, with a role of ubiquitin-dependent proteasomal degradation at early stages of infection." (PMID 29487367, 2018). "At early stages of infection (4 hpi), we observed a faster decrease of Mdm2 RPL on infected versus mock conditions, with an estimated half-life of 12 and 50 min (P < 0.001), respectively." (PMID 29487367, 2018). "Our results indicate that Mdm2 stability is modulated during infection, with a marked degradation at early stages of infection." (PMID 29487367, 2018). "We next investigated the interaction between RPLs (RPL11 and RPL23) and MDM2 during different time points post-infection (8 hpi and 24 hpi)." (PMID 29259342, 2017). "Our result showed that in BACEBV-GFPWT infection, mdm2 transcripts were found to be upregulated from 2 dpi (4.9 fold) to 5 dpi (22 fold) and get down regulated at 7 dpi (0.9 fold)." (PMID 26908453, 2016). "A similar trend of Mdm2 protein expression was found in BACEBV-GFPWT infection, as we found at transcript level." (PMID 26908453, 2016). "MDM2 expression was reduced after infection and increased with emetine treatment at 72 hpi in high-density cells." (PMID 27336364, 2016). "Infection of adeno-MDM2 (Ad-MDM2) reduced exogenous HDAC1 protein expression by Ad-HDAC1 in a dose-dependent manner in RVSMCs." (PMID 26832969, 2016). "MDM2 polymorphism was detected by PCR- RFLP and infection of Helicobacter pylori (H. pylori) by a validated serology test." (PMID 23506213, 2013). "Following infection with Ras virus, we observed comparable cell cycle arrest in Mdm2+/+ and Mdm2C305F/C305F MEFs as evidenced by a similar decrease in cell number." (PMID 21747916, 2011). "However, while the consequences of this site for SARS-CoV-2 infection have not been investigated so far, the regulation of ACE2 levels by MDM2-dependent ubiquitination is in line with our infection experiments." (PMID 37632105, 2023). "LY6E has been shown to specifically impair SARS-CoV-2 entry, and—given the similarity of the infection phenotype in our live-cell imaging screen —we speculated that MDM2 might be involved in virus uptake." (PMID 37632105, 2023). "According to the ambivalent role of apoptosis during IAV infection, MDM2 could be used by NS1 at early stages of infection to promote IAV propagation." (PMID 34835115, 2021). "In this regard, upon curcumin-induced inhibition of MDM2 expression, influenza virus infection may lose its target of interaction, resulting in reduced infection." (PMID 34577580, 2021).
infection (continued). "To further characterize the impact of infection on Mdm2 expression, we mock-infected or infected A549 cells to reproduce different viral conditions of marked decrease (MOI 4, 4 and 8 hpi) or increase (MOI 0.1, 24 hpi) of Mdm2 RPL compared to mock and measured Mdm2 mRNA levels by RT-qPCR." (PMID 29487367, 2018). "At late stages of infection (24 hpi), we observed a stronger increase of global Mdm2 staining, yet with partial relocalization of Mdm2 in the cytoplasm of several infected cells, as well as a relative exclusion between cytoplasmic Mdm2 and nuclear NS1 respective stainings." (PMID 29487367, 2018). "The infection of T-cell lines and primary CD4+ T cells with HIV was initially reported to be associated with stronger expression of pro-apoptotic genes, such as those encoding Bax, p21 and MDM2." (PMID 23658518, 2013). "This suggests the possibilities that the ubiquitination of Tat might work as a positive regulatory factor at an earlier phase of infection and that MDM2 might be involved in both positive and negative regulation of HIV-1 replication at different stages." (PMID 19128510, 2009). "Genetic depletion of MDM2 elevated ACE2 expression levels, which strongly promoted infection with all SARS-CoV-2 isolates tested." (PMID 37632105, 2023). "To confirm that MDM2 may target K788 for ubiquitination and subsequent degradation of ACE2, we mutated Lysine 788 into Arginine (K788R), following the hypothesis that preventing MDM2-dependent ubiquitination would stabilize ACE2 and lead to overall higher infection rates." (PMID 37632105, 2023). "Both infection-induced MDM1 and MDM2 populations have high signature scores for pro-inflammatory pathways such as an INFγ response, TNFα signaling via NF-kB, and general inflammatory responses." (PMID 36420267, 2022). "We then co-transfected MDM2, or both MDM2 and HBP1 into H1299 cells, and knocked down MDM2, or both MDM2 and HBP1 through lentiviral infection." (PMID 30816344, 2019).
infection (continued). "At a multiplicity of infection (MOI) of 0.1, we observed a dramatic decrease of up to 5-fold in Mdm2 endogenous protein levels at 2 h post-infection (hpi), compared to the mock-infected control." (PMID 29487367, 2018). "Although the expression of mdm2 was less in EBVGFPΔE3C130-159 virus at 2 dpi (1.2 fold) and 5 dpi (12 fold), the trend was similar as we found in BACEBV-GFPWT infection." (PMID 26908453, 2016). "By contrast, Mdm2 expression was downregulated in HCMV-infected HepG2 cells at day 4 and day 6 post-infection." (PMID 23555719, 2013). "Importantly, our study also highlighted MAVS and MDM2 genes with common DRE sites across different ocular SARS-CoV-2 infections, pointing to common regulatory mechanisms in these tissues during the infection." (PMID 38693480, 2024). "Between three and five weeks after infection, SiglecF–CD11c+ non-AM macrophages (i.e., MDM2) underwent a 14-fold increase in cell number such that they accounted for ~14% of the lung myeloid cells." (PMID 38977711, 2024). "The comparable infection kinetics and specificity in MDM2 and LY6E-depleted cells led us to hypothesize that MDM2 may impair SARS-CoV-2 uptake, as reported for LY6E." (PMID 37632105, 2023). "MDM1 and MDM2 subpopulations express genes enriched for INFɣ responses, TNF signaling via NF-κB, and inflammatory responses, suggesting the immune stimulating function of these cells during infection." (PMID 36420267, 2022). "Although Mdm2 relative protein levels (RPL) remained below 50% at least for the following 8 h, a more than 1.5-fold increase compared to mock was observed 24 h after infection (P < 0.01)." (PMID 29487367, 2018). "As in HeLa cells, CTL2 infection did not influence totalcellular MDM2 levels ofprimary fallopian tube mesenchymal cells." (PMID 25392082, 2014). "In a single round infection assay, in the absence of A3G, viral replication was not affected by expression of MDM2 and/or Vif (lanes 1–6)." (PMID 19128510, 2009). "Therefore, the knockout of MDM2 could increase the expression levels of ACE2, plausibly explaining enhanced infection and selective uptake of SARS-CoV-2." (PMID 37632105, 2023). "Notably, western immunoblotting of the samesamples using antibodies to detect total MDM2 levels showed no change following infection." (PMID 25392082, 2014).
infection (continued). "In addition to revealing the TRAF-2 and TRAF-6 ubiquitin ligase complexes, which have known roles in immune signaling during infection, this analysis identified ubiquitin ligase complexes, including CUL3, RBX1, and MDM2, that have not been previously implicated in Mtb pathogenesis." (PMID 31951200, 2020).